PRMT5 (protein arginine methyltransferase 5)
Diseases named in the same sentence as PRMT5 in open-access papers (continued):
Sharing a sentence is not in itself a finding about the gene and the disease.
cancer (continued). "The PRMT family, particularly PRMT5, has been extensively researched in cancer therapy due to its implication in the regulation of cancer-related processes such as transcription, DNA repair, and RNA metabolism." (PMID 37667522, 2023). "A PubMed search with the prompt “PRMT5 cancer” retrieves over 500 articles highlighting the importance of this gene in cancer." (PMID 37047013, 2023). "Recently, our group revealed that T cell-specific deletion of Prmt5 promoted T-cell differentiation into Klrg1+ terminal T cells and promoted cancer progression." (PMID 37533053, 2023). "The role of Prmt5 as a cancer driver has been well studied, and Prmt5 inhibitors to treat cancers are currently being assessed in clinical trials." (PMID 37533053, 2023). "In this review, we focus on the role of a major type II PRMT, PRMT5, recognized as an anti-cancer target that has recently gained significant interest." (PMID 36980950, 2023). "The type 1 PRMT inhibitor, GSK3368715 was analyzed in 249 cancer cell lines representing 12 different tumors and was shown to have significant tumor‐suppressive activity, that synergizes on the addition of a PRMT5 inhibitor (GSK3368715)." (PMID 35747993, 2023). "PRMT5, a major type II methyltransferase, is widely expressed in human cancers and has a crucial role in cancer development." (PMID 37400960, 2023). "The higher expression of PRMT5 in cancer is thought to epigenetically suppress tumor suppressor and cell cycle genes." (PMID 38136401, 2023). "In a previous study, it was known that histone H3 and H4 methylation by PRMT5 in combination with MEP50 regulates the transcription of genes involved in cancer cell metastasis and EMT response related to TGF-β signaling." (PMID 36765032, 2023). "PRMT5 inhibition by JNJ-64619178 led to a significantly smaller number of colonies compared to vehicle (DMSO) treated groups in all the cancer cell lines, which indicates that JNJ-64619178 is successfully rendering the cancer cells sensitive to IR treatment." (PMID 36959798, 2023). "PRMT5 expression is ubiquitous and its overexpression in cancers correlates with disease progression and worse prognosis." (PMID 37861290, 2023). "The arginine residue of E2F1, a key molecule in cancer cell growth, is the target of methylation by PRMT5." (PMID 36765032, 2023). "PRMT5 is necessary for regulatory T cell (Treg) functions and promotes cancer stemness and the epithelial–mesenchymal transition." (PMID 36980950, 2023). "A pre-clinical study using a combination of inhibitors of PRMT1 (MS023) and PRMT5 (EPZ015666) demonstrated an efficient anti-cancer effect in lung cancer and pancreatic cancer cell lines." (PMID 37568815, 2023). "The effect of PRMT5 inhibition on blockade of the G1-to-S transition in RB1-deleted cells suggested a novel approach to suppress cancer cell proliferation." (PMID 37502925, 2023). "This indicates a critical role for PRMT5 methylation in the pathogenesis of hemoglobinopathies and cancer." (PMID 37928266, 2023). "PRMT5 has a nuclear localization, and its expression correlates with poor survival in several types of cancers." (PMID 36982984, 2023). "For instance, the PRMT5-specific inhibitor GSK3326595 has entered into phase II clinical trials for cancer therapy." (PMID 37173306, 2023). "The goal of this study was to explore the role and mechanism of PRMT5 in cell metabolism, cancer progression, and asses its potential as a therapeutic target." (PMID 36999124, 2023). "The importance of arginine methylation by PRMT5 in cancer progression has only recently become apparent." (PMID 38136401, 2023). "PRMT5 overexpression is observed in a wide variety of cancers and is involved in the maintenance of the TME." (PMID 36980950, 2023). "Homologous deletions of MTAP are found in 40% of GB cases, resulting in a dependence of cancer cells on Protein Arginine Methyltransferase 5 (PRMT5)." (PMID 37298093, 2023).
cancer (continued). "Based on safety, clinical activity, and PK and pharmacodynamic (PD) outcomes, two RP2Ds (1.5 mg intermittently and 1 mg once daily) were selected to inhibit PRMT5 activity in patients with cancerous tumors." (PMID 38136401, 2023). "Genetic alterations in PRMT5 genes are rare and thus control of PRMT5 in cancer has emerged as an attractive cancer therapeutic." (PMID 36819050, 2023). "Studies support the predictive value of PRMT5 overexpression as a biomarker for aggressive tumorigenesis in cancer patients." (PMID 38136401, 2023). "In this report, we queried the Catalogue of Somatic Mutations in Cancers (COSMIC) and characterized all PRMT5 mutations." (PMID 37047013, 2023). "Recent studies have shown that PRMT5 is involved in developing and progressing various types of cancer, including breast, lung, prostate, colorectal, and gastric cancer, among others." (PMID 37400960, 2023). "As PRMT5 inhibitors are in clinical trials for various cancers, studies that identify putative patient populations will be critical to ensure therapeutic success without associated toxicities." (PMID 36980782, 2023). "In this review article, we present the current evidence revealing that PRMT5 is involved in cancer immunology." (PMID 36980950, 2023). "PRMT5 is an inhibitor of tumor suppressor genes and thus enables the unchecked proliferation of cancer cells." (PMID 36913304, 2023). "PRMT5 is considered as an oncogene and overexpressed in many human cancers, but the role of PRMT5 in angiogenesis is still unclear." (PMID 37400960, 2023). "High expression of PRMT5 correlating with poor prognosis has been detected in many cancers, suggesting that PRMT5 has oncogenic function." (PMID 37047013, 2023). "PRMT5 inhibitors are a promising class of anti-cancer drugs demonstrating preclinical and preliminary clinical efficacies." (PMID 38136401, 2023). "The type II methyltransferase PRMT5 has diverse effects on cancer biological functions, such as histone methylation and inhibition or promotion of tumor-associated signaling pathways." (PMID 36765032, 2023). "PRMT5 loss is synthetically lethal with MTAP deficiency, which occurs frequently in many cancer types, including PCa, providing an additional rationale for the use of PRMT5 inhibitors in selected patient populations." (PMID 38201511, 2023). "PRMT5 promotes cancer cell growth and survival by regulating the expression of various oncogenes and tumour suppressor genes." (PMID 37461162, 2023). "Cancer cell xenograft tumor analysis revealed that PRMT5 inhibitor (DS-437) treatment shrunk the tumor mass." (PMID 36980950, 2023). "PRMT5 ablation alone also recapitulates FA pathway deficiency seen in MTAP-deleted tumors, mimicked by the use of MAT2A inhibitors in MTAP-deleted cancers that was found to be synergistic with docetaxel in squamous lung and pancreatic PDX models." (PMID 37861290, 2023). "Antagonization of PRMT5 enzymatic activity has demonstrated great promise in a multitude of pre-clinical cancer studies [reviewed in." (PMID 36819050, 2023). "Pharmacological inhibition of PRMT5 has been shown to inhibit cancer-specific splicing patterns and inhibit cancer cell growth." (PMID 36979496, 2023). "Accordingly, PRMT5 inhibition is being explored as a cancer therapy and several PRMT5 inhibitors have been tested in clinical trials." (PMID 37861290, 2023). "The inhibition of PRMT5 as well as PRMT1 and CARM1 have been shown to cause splicing inhibition and display anti-cancer properties in several cancers." (PMID 37568815, 2023). "Our study has connected the pRb-E2F pathway and PRMT5, a key cancer-relevant enzyme, with control of lncRNA gene expression." (PMID 36841868, 2023). "The splicing landscape is an especially understudied area of CSC biology even though small molecule inhibitors against key enzymes that regulate splicing, such as PRMT5, are in clinical trials for cancer treatment." (PMID 36980782, 2023).
cancer (continued). "The depletion or chemical inhibition of PRMT5 inhibits splicing and produces anti-cancer effects in various cancers." (PMID 37630236, 2023). "Clinical trials are underway to evaluate the effectiveness of PRMT5 inhibitors in treating different types of cancer." (PMID 37684587, 2023). "Recently, arginine methyltransferase-5 (PRMT5) has been described as a potential target for cancer treatment." (PMID 36982984, 2023). "Significantly, the overexpression of PRMTs in cancer is often linked to poor prognosis, and PRMT inhibitors, especially against PRMT5, are currently being tested in clinical trials with cancer patients." (PMID 38134182, 2023). "Future generations of drugs that target PRMT5 activity in an MTAP-negative background must focus on maximising their selectivity for inhibiting PRMT5 specifically within the cancer cell (i.e. when PRMT5 is bound to MTA)." (PMID 37795443, 2023). "Nuclear factor-kappa B (NF-κΒ) and protein arginine methyltransferase 5 (PRMT5) function as oncogenes in many types of cancer." (PMID 37444594, 2023). "In this work, we highlighted evidence that PRMT5 inhibitors broadly and potently downregulate core DDR pathways in ovarian, breast, and other cancers resulting in a DNA repair–deficient phenotype." (PMID 37861290, 2023). "The evolving evidence suggests that the role of PRMT5 in cancer development has recently gained significant attention." (PMID 37400960, 2023). "It's commonly recognized that PRMT5 is an important oncogene, and several small-molecule inhibitors targeting PRMT5 have been identified for cancer patients." (PMID 37781030, 2023). "This suggests that changes in the coding sequence of PRMT5 are more frequent in cancers, implying a potential role in cancer development." (PMID 38203325, 2023). "We found that the expression of PRMT5 was significantly lower in cancer, compared with the adjacent normal tissues." (PMID 37781030, 2023). "A growing amount of evidence reveals that PRMT5 is overexpressed or activated in a variety of cancers." (PMID 37173967, 2023). "PRMT5 is one of the methyltransferases initially identified in yeast with pleiotropic functions in humans, including in development and cancer." (PMID 37047013, 2023). "Dysregulated PRMT5 expression has been described in a variety of cancers; overexpression being correlated with poor survival rates." (PMID 37536978, 2023). "Further efforts are necessary to identify alternative means of targeting PRMT5 and MTA2 in MTAP-ve cancers to benefit from the high-MTA environment of MTAP-deficient cancers." (PMID 36913304, 2023). "This makes PRMT5 a good candidate for cancer therapy, and consequently, many compounds have been screened to find the required specificity and efficacy for GBM treatment." (PMID 36982984, 2023). "PRMT5 has also been shown to directly methylate Akt1 arginine 15, a master regulator for cancer metastasis, leading to cancer cell invasion and migration." (PMID 37400960, 2023). "PRMT5 is mostly upregulated and has multiple roles in cancer, including histone methylation, transcriptional regulation, signal transduction, DNA damage, and splicing." (PMID 36765032, 2023). "In GSE14520, the expressions of PRMT1, PRMT3, PRMT4, and PRMT5 were upregulated in cancer tissues, whereas PRMT2 and PRMT8 were downregulated." (PMID 37627211, 2023). "Ongoing extensive research is dedicated to deciphering the intricate mechanisms by which PRMT5 influences tumor formation, offering promising avenues for developing targeted and effective cancer treatments." (PMID 38203325, 2023). "Overexpression of PRMT5 has important consequences for the epigenetic landscape of cancer across different cancer types." (PMID 37795443, 2023). "MTA accumulation in MTAP deleted cells creates a hypomorphic PRMT5 state that is sensitized towards further PRMT5 inhibition making PRMT5 inhibitors a potential therapy for MTAP deleted cancers." (PMID 36913304, 2023).
cancer (continued). "As PRMT5 was reported to have oncogenic properties, several PRMT5 inhibitors have been developed as potential therapeutic strategies to treat diverse cancers; three agents are currently being tested in human clinical trials." (PMID 37458145, 2023). "The effects of PRMT5 inhibition on cancerous cells’ proliferation, invasion, and migration can contribute to anti-cancer efficacy." (PMID 38136401, 2023). "Protein arginine methyltransferase 5 (PRMT5) expression is significantly upregulated in a variety of cancer cells." (PMID 37601696, 2023). "We evaluated the Pearson’s correlation coefficients of PRMT5 using RNAseq data from matched pairs of normal and carcinoma tissues (columns 2 and 3)." (PMID 37887269, 2023). "As a well-known oncogenic enzyme, PRMT5 is ubiquitously expressed in the cytoplasm and nucleus of carcinoma cells." (PMID 36878903, 2023). "Although MTAP deletion sensitizes cancer cells to PRMT5 depletion, pharmacologic inhibition of PRMT5 by a specific small‐molecule inhibitor shows only modest selective tumor cytotoxicity." (PMID 35766227, 2022). "H3K27me3 methyltransferase and demethylase inhibitors (UNC1999 and GSKJ4) as well as a PRMT5 inhibitor (GSK591) also had antiproliferative effects on a wide variety of cancer cells, including TNBC7,19,20." (PMID 35578032, 2022). "An increased activity and overexpression of PRMT5 was identified in several cancers, making it a promising drug target." (PMID 36232624, 2022). "The octamer methylates a broad spectrum of substrates, including COPR546, SWI/SNF47, pICln48, Riok149, Menin50, etc., and making targeted PRMT5 inhibition a potential cancer therapy." (PMID 36192627, 2022). "PRMT5 has emerged as a possible cancer drug target and PRMT5 inhibitors are potent in clinical trials for blood and multiple solid malignancies." (PMID 35655230, 2022). "From drop-out screens in multiple cell lines, we identified novel epigenetic modifiers for cancer cell fitness as well as the previously studied ones such as PRMT5, HDAC3, FOXA1 and LSD1." (PMID 35973998, 2022). "Studies have also shown that SHARPIN can interact with PRMT5, which can facilitate the transcription of regulatory cancer-related genes." (PMID 35547743, 2022). "The methyltransferases PRMT1 and PRMT5 have been shown to be overexpressed in many cancers and to regulate cancer cell migration and invasion." (PMID 36555834, 2022). "There is an abundance of evidence suggesting that PRMT5 plays an oncogenic role in many cancers such as prostate cancer, pancreatic cancer, and colorectal cancer." (PMID 35118387, 2022). "In MTAP-deficient cancers, MTA accumulation selectively inhibits protein arginine methyltransferase 5 (PRMT5) enzyme activity and increases PRMT5 inhibition sensitivity." (PMID 35979371, 2022). "Since several PRMT5 inhibitors are in ongoing preclinical and clinical studies for the treatment of cancer, it is worth observing potential side effects on the endometrium and reproductive capacity." (PMID 36195592, 2022). "PRMT5 is overexpressed in a wide variety of cancers, such as lung, breast, gastric and liver cancer." (PMID 35655230, 2022). "Deletion of MTAP results in increased dependency on PRMT5 in cancer cells thus providing the potential avenues for targeted therapies." (PMID 36572880, 2022). "Protein arginine methyltransferase 5 (PRMT5) is upregulated in multiple tumors and plays a pivotal role in cancer cell proliferation." (PMID 36474242, 2022). "Protein arginine methyltransferase 5 (PRMT5) is an epigenetic regulator which has been proven to be a potential target for cancer therapy." (PMID 36499164, 2022). "Of note, the tumor-promoting function of PRMT5 was observed in the in vitro experiments of cancer cell lines 13-19." (PMID 35864961, 2022). "Considering that PRMT1, PRMT4, and PRMT5 have the highest expression in cancer, their immunosuppressive effect have been well investigated." (PMID 36713412, 2022).
cancer (continued). "PRMT5 knockdown down-regulated PI3K/AKT/mTOR signaling in an influx of cancer cells, including bladder cancer, lymphoma, and Non-small-cell lung carcer (NSCLC)." (PMID 35493527, 2022). "The intense involvement in cancer pathology has led to an increasing recognition of PRMT5 being a novel holy grail target for the development of chemotherapeutics." (PMID 35744905, 2022). "In laryngeal SCC chemotherapy-resistant patients, FOXD2-AS1 showed increased expression and acted as a scaffold for STAT2 and PRMT5, both essential to maintain cancer stemness and promote chemotherapy resistance." (PMID 35978835, 2022). "Regarding arginine methylation, studies have shown that PRMT5 is involved in the dysregulation of metabolism in cancer cells." (PMID 35681635, 2022). "Several PRMT5 substrates were in common with cancer cell lines and related to RNA processing, splicing and transcription." (PMID 35370564, 2022). "The growth of MTAP-deleted cancer cells is blocked as a result of MAT2A inhibition which lowers PRMT5-dependent mRNA splicing and prompts DNA damage." (PMID 36572880, 2022). "Overexpression or elevation in enzymatic activity of PRMT5 has been observed in various types of cancers, exacerbating the progression of tumors." (PMID 35766227, 2022). "Here, we identified Cancer/Testis Antigen gene family 47 (CT47) as an essential regulator of human-specific spermatogenesis by stabilizing arginine methyltransferase 5 (PRMT5)." (PMID 35918318, 2022). "Nevertheless, since a few PRMT5 inhibitors are currently being tested in clinical trials (e.g., GSK3326595 and JNJ-64619178) 62, 63, our findings raised a concern about PRMT5 being a therapeutic target of cancer, at least in gastric tissue." (PMID 35864961, 2022). "A synergistic cancer cell growth inhibition effect was observed when PRMT5 was inhibited with GSK3368715, which further indicated the therapeutic value of type I and type II PRMTs." (PMID 35429301, 2022). "PRMT5, an oncogenic target for various cancer types, has many inhibitors manifesting little cooperativity with MTA, a co-factor analog accumulated in MTAP−/− cells." (PMID 36192627, 2022). "PRMT5 is a promising drug target, playing a role in the pathomechanism of several diseases, especially in the progression of certain types of cancer." (PMID 36232624, 2022). "EPZ015666 (GSK3235025) is a potent PRMT5 inhibitor that is under clinical investigation for cancer treatment." (PMID 35531958, 2022). "PRMT5, as a tumor-promoting factor, is overexpressed in numerous cancers, including HCC, by participating in processes such as viral carcinogenesis, cell cycles, and spliceosome assembly." (PMID 36499164, 2022). "When the cancer cell has an abundance of intracellular glucose, PRMT5 works to promote its transition from the G1 to the S phase by upregulating CDK4." (PMID 35681635, 2022). "Collectively, these lines of evidence demonstrate the extensive oncogenic role of PRMT5 in cancers and its potential value as a clinical biomarker to improve patients’ treatment modalities." (PMID 34685445, 2021). "PRMT5 has emerged as an important player in HCC, the fourth leading cause of cancer mortality in the world." (PMID 33768972, 2021). "In MTAP deleted cancers, PRMT5 and methionine adenosyltransferase II α (MAT2A) enzymes were identified as synthetic lethal targets." (PMID 34573422, 2021). "It would be of great significance to investigate the effects of PRMT5 inhibitors in cancer types with aberrantly hyperactivated STAT3 signaling." (PMID 34026434, 2021). "MRTX9768, a compound developed by Miratis Therapeutics, Inc., is focused on inhibiting the methylthioadenosine phosphorylase (MTA)-PRMT5 complex in MTAPdel cancer cells, resulting in their targeting for destruction." (PMID 34685445, 2021). "The epigenetic regulation of cancer-specific miRNA expression by PRMT5 is critical for tumor growth, progression, and metastasis." (PMID 34006904, 2021).